CCR9 (C-C motif chemokine receptor 9)
Diseases named in the same sentence as CCR9 in open-access papers (continued):
Sharing a sentence is not in itself a finding about the gene and the disease.
Crohn disease (20 papers, 2008 to 2023). A gastrointestinal disorder characterized by chronic inflammation involving all layers of the intestinal wall, noncaseating granulomas affecting the intestinal wall and regional lymph nodes, and transmural fibrosis. "The mention of a clinical trial involving an anti-MadCam1 drug and its impact on CCR9 expression in active Crohn’s disease (aCD) patients is significant." (PMID 37893204, 2023). "CCR9 plays a critical role in the homing of lymphocytes into inflamed intestines, thereby contributing to the pathogenesis of colitis and Crohn’s disease." (PMID 35677056, 2022). "The levels of colonic CCL25 had been shown to increase in both Crohn’s disease and ulcerative colitis, and pharmacological inhibitors of CCR9 prevented the development of ulcerative colitis in an experimental model." (PMID 27832135, 2016). "Their findings indicated that patients with active UC and Crohn’s disease had a significant increase in the expression of C-C chemokine receptor type 9 (CCR9)." (PMID 27303404, 2016). "The reduced levels of IFN-γ are noteworthy, as CCR9+ cells have been shown to be a significant source of this cytokine in Crohn's disease." (PMID 26457007, 2015). "In support of this approach, a small molecule antagonist of CCR9 has shown promise in clinical trials for Crohn's disease, a complex, heterogeneous inflammatory disorder of the digestive tract." (PMID 25437209, 2014). "It was also shown that the percentage of CCR9-positive lymphocytes increased in murine model of Crohn's disease, and neutralization of the receptor or the chemokine attenuated early disease." (PMID 21249211, 2011). "An oral CCR9 antagonist (CCX282-B) is currently used in a Phase II clinical trial for the treatment of Crohn's disease and has shown efficacy in the treatment of patients with moderate to severe small bowel Crohn's disease." (PMID 21283540, 2011). "In peripheral blood lymphocytes, CCR9-positive T cells were markedly elevated in patients with Crohn's disease." (PMID 21249211, 2011). "CCX282-B (Traficet-EN, ChemoCentryx) is a small molecule that can antagonize CCR9 function and has already shown promising results in a phase II clinical trial of moderate to severe Crohn's Disease patients as it successfully delays disease progression." (PMID 21283540, 2011). "In inflammatory gut disease, CCR9+ T cells are more abundant in the PB of patients with celiac disease or Crohn's disease." (PMID 20738854, 2010). "There is currently a CCR9 antagonist that shows promise in clinical trials for Crohn's disease, in fact this is one of the few clinical trials targeting chemokine receptors that show hope in the treatment of inflammatory diseases." (PMID 20738854, 2010). "CCR9 is known to be involved in homing of T cells and plasma cells to the intestine, and plays a role in inflammatory diseases of the gut such as Crohn's disease." (PMID 18698345, 2008). "Indeed, in the PROTECT-1 clinical trial, pharmacological inhibition of CCR9 resulted in a significant reduction in disease severity in Crohn's disease subjects, relative to those on placebo." (PMID 26457007, 2015). "However, contradicting results have emerged in the role of CCL25/CCR9 interactions in the experimental small intestinal inflammation of the TNFΔare mouse model that mimics human Crohn's Disease." (PMID 21283540, 2011). "However, the percentage of CCR9+ T lymphocytes was shown to be reduced in the small intestine with Crohn's disease whereas in the present study the percentage of CCR9+ macrophages in RA ST did not reduce compared with normal, but was increased." (PMID 20738854, 2010). "Among the allosteric CCR9 antagonists, the most interesting are vercirnon, which has a very high selectivity for binding to CCR9, and its analogs (including 4-aminopyrimidine derivatives), which may be useful in the treatment of Crohn’s disease." (PMID 37047169, 2023).
Crohn disease (continued). "Treatment with CCR9 antagonist did not accompany critical infections as an adverse effect in a large phase II study for Crohn’s disease." (PMID 25248373, 2014). "Blocking CCR9 is a new approach to Crohn’s disease therapy and a test of this mechanism has not been attempted previously in clinical trials." (PMID 23527300, 2013). "The fact that these studies were focused on small intestinal but not large intestinal inflammation, made CCL25 and CCR9 attractive candidates for the treatment of Crohn's disease but not ulcerative colitis." (PMID 21283540, 2011). "An orally bioactive inhibitor of CCR9, CCX282, has been developed and was well tolerated with encouraging results in clinical trials for Crohn’s disease, but no studies in treatment of GVHD has been reported so far." (PMID 35677056, 2022).
breast cancer (14 papers, 2013 to 2022). A primary or metastatic malignant neoplasm involving the breast. "The highest number of SBs was predicted in colon cancers from the 6 cancer-specific proteins, covering all the evaluated HLA alleles; the lowest number was predicted in breast cancer from the single CCR9 cancer-specific protein." (PMID 36243758, 2022). "According to such additional filter, six cancer-specific proteins in colon cancer (CEACAM8, CDH17, GLOD5, PPM1E, TRIM16, EPCAM) and one in breast cancer (CCR9) were identified." (PMID 36243758, 2022). "The limited number of HLA-A*24:02 HIV-positive subjects does not provide the sufficient statistical power for the trend observed with CCR9 breast cancer paired peptides." (PMID 36243758, 2022). "CCL25/CCR9 signaling can promote the migration and invasion of breast cancer cells to the bone by regulating numerous markers of epithelial–mesenchymal transition (EMT)." (PMID 33435254, 2021). "The CXCL12/CXCR4 axis is strongly correlated with breast cancer aggressiveness and metastasis, whereas the CCL25/CCR9 axis provides chemotherapy resistance to breast cancer cells." (PMID 31616626, 2019). "CCR9 inhibition in MDA-MB-231 metastatic breast cancer cell line also resulted in marked increase in immune-mediated tumor lysis (Fig4E)." (PMID 25691366, 2015). "A recent study suggests that CCR9 may promote metastasis in breast cancer by enhancing cell migration, increasing matrix-metalloproteinase-9 (MMP-9) expression via CCL25 and supporting tumor cell survival in metastatic sites." (PMID 24259307, 2013). "However, more comprehensive investigations into this signal are required to confirm its role in bone metastasis, and it is still uncertain whether the CCR9 antibody is useful for treating breast cancer with bone metastasis." (PMID 33435254, 2021). "CCR9/CCL25 also has an important role in tumor invasion and metastasis by promoting EMT in liver, non-small cell lung cancer, and breast cancer cell lines." (PMID 33034614, 2020). "According to such parameters, six cancer-specific proteins in colon cancer (CEACAM8, CDH17, GLOD5, PPM1E, TRIM16, EPCAM), one in breast cancer (CCR9) and none in prostate cancer were identified." (PMID 36243758, 2022). "Interestingly, shRNA-mediated stable knockdown of CCR9 did not affect CCL25 production by MCF7 breast cancer cells (Fig6A)." (PMID 25691366, 2015).
ovarian carcinoma (14 papers, 2010 to 2024). A malignant neoplasm originating from the surface ovarian epithelium. "Specific examples include CCL5 and CCL25 and their cognate receptors CCR5 and CCR9 in breast and ovarian cancers, respectively." (PMID 29358632, 2018). "Certain ovarian cancer cell lines and tumors also express CCR9; however, further research is needed to elucidate the role of CCR9 in other cancers and to determine the mechanism by which it promotes metastasis." (PMID 24259307, 2013). "In patients with breast or ovarian carcinomas, higher CCR9 expression in cancer tissues correlate with disease severity, and CCR9 expressing cancer cells migrate and invade under a chemotactic gradient of CCL25 via up-regulation of matrix metalloproteinases (MMPs)." (PMID 25296976, 2014). "We have shown that ovarian cancer cells express CC chemokine receptor-9 (CCR9)." (PMID 20565782, 2010). "The expression of CCR9 and CCL25 have been identified in some solid tumors, including ovarian cancer 9, breast cancer 10, prostate cancer 11, pancreatic cancer 12 and esophageal cancer." (PMID 32308544, 2020). "The correct reference is “Singh, R.; Stockard, C.R.; Grizzle, W.E.; Lillard, J.W., Jr.; Singh, S., Expression and histopathological correlation of CCR9 and CCL25 in ovarian cancer." (PMID 31146450, 2019). "Reference 98 to “Singh, R.; Stockard, C.R.; Grizzle, W.E.; Lillard, J.W., Jr.; Singh, S., Expression and histopathological correlation of CCR9 and CCL25 in ovarian cancer." (PMID 31146450, 2019). "Studies have found that the interaction of CCL25/CCR9 can increase the expression of MMP-2 and MMP-9, which induce tumor metastasis in a variety of cancers, such as ovarian cancer, prostate cancer, non-small cell lung cancer, and endometriosis." (PMID 26879872, 2016). "Another study on ovarian cancer showed a significant increase in CCR9 expression in seromucous carcinoma tissues compared to nontumorous tissues." (PMID 39411316, 2024). "Recent studies have shown that CCL25/CCR9, via activating the PI3K/AKT signaling pathway, mediated anti-apoptotic processes in lung cancer, induced etoposide resistance in prostate cancer, and induced cis-platinum resistance, which is dependent on PI3K and not FAK, in breast and ovarian cancer." (PMID 26879872, 2016).
Arthritis (11 papers, 2014 to 2024). Inflammation of a joint. "In our study, we analyzed the effectiveness of using dendritic cells transfected with DNA constructs encoding IL-10, type II collagen, and CCR9 to induce immune tolerance in an experimental model of arthritis." (PMID 39161770, 2024). "The clinical arthritis scores in the CCR9-deficient mice were significantly lower than those in the WT." (PMID 25248373, 2014). "To conclude, DCs transfected with DNA constructs encoding epitopes of type II collagen, IL-10, and CCR9 promote antigen-specific tolerance, control inflammation, and reduce the severity of experimental arthritis through the induction of T regulatory cells, IL-10, and TGF- β." (PMID 39161770, 2024). "The administration of CCR9 antagonists or the suppression of CCR9 expression has demonstrated the potential to alleviate arthritis symptoms in mice." (PMID 37798668, 2023). "CCR4, CCR6, CCR7, CCR9, CXCR5, and CXCR6 deficiency ameliorated arthritis in CIA mice by suppressing the migration of Th17 cells (CCR4), DC (CCR7), and CD11b+ splenocytes (CCR9)." (PMID 36860872, 2023). "CCR9 antagonist (CCX8037) also suppressed collagen-induced arthritis and decreased the migration of CD11b+ splenic cells to synovial tissues." (PMID 34490243, 2021). "The percentages of CCR9 positive cells in inflamed synovial fluid were more than doubled as compared to the blood of arthritis patients." (PMID 25251539, 2014). "In this study, we showed that the abrogation of CCR9 ameliorated arthritis in a murine model of RA." (PMID 25248373, 2014). "This could reflect the general hyperlipidemia of atherosclerotic patients and may explain the increase in CCR9 expression in peripheral blood of arthritis patients." (PMID 25251539, 2014). "Moreover, inhibition of CCR9 reduced arthritis and inflammatory cell migration in mice." (PMID 25248373, 2014). "Given the observed expression of CCR9 and α4β7 on CD161+ Tconv and CD161+ Treg in blood, and the suggested link between arthritis and gut inflammation, we next examined the expression of these receptors on CD161+ Tconv and CD161+ Treg from patients with autoimmune arthritis." (PMID 28321213, 2017). "It was reported that deficiency of CCR9, as well as CCR1, CCR2 and CCR5, did not attenuate a murine model of serum transfer arthritis." (PMID 25248373, 2014).
prostate carcinoma (11 papers, 2010 to 2022). A carcinoma that arises from epithelial cells of the prostate gland. "Therefore CCR9 has mainly been reported to function in lymphocyte migration although other cell types, such as tumour cells, can express CCR9, playing a role in prostate cancer cell migration and invasion." (PMID 20738854, 2010). "Prostate cancer cells highly expressing CCR9 could promote tumor cell migration and invasion." (PMID 32308544, 2020). "For example, it was shown to function through being regulated by inflammatory cytokines (IL-6, CCR9 and TLR3) during apoptosis, and involve in the pathogenesis of prostate cancer." (PMID 28545028, 2017). "We have previously shown that CCR9 and CCL25 play significant role in prostate cancer cell survival, which is required for cancer cells to achieve their metastatic goal." (PMID 25296976, 2014).
leukemia (10 papers, 2013 to 2024). A malignant (clonal) hematologic disorder, involving hematopoietic stem cells and characterized by the presence of primitive or atypical myeloid or lymphoid cells in the bone marrow and the blood. "Taken together, these data suggest that the humanized version of 92R mAb (Srb1), display a strong therapeutic potential for the treatment of CCR9+ leukemias and other CCR9+ tumor types." (PMID 35967322, 2022). "Our studies have shown that CCL25 induces MOLT4 cells (human T-ALL cell line with naturally high expression of CCR9) polarization and microvilli absorption to participate in leukemia infiltration and trafficking via the RhoA-Rock-MLC and ezrin pathway." (PMID 33743810, 2021). "We also found that the combined use of IL-2 and IL-4 promoted the internalization of CCR9 and therefore attenuated leukemia cell infiltration and metastasis." (PMID 33743810, 2021). "Many chemokine axes such as CXCL12/CXCR4 and CCL25/CCR9 have been proved to play important roles in leukemia microenvironment and further affect ALL outcomes." (PMID 33743810, 2021). "These shPten leukemias expressed high levels of CCR9 and showed marked dissemination to the intestine (and liver)." (PMID 29666622, 2018). "We also found that T-ALL cells can increase the expression of IL-4 after treatment with IL-2 and that IL-2 can activate the PKC and GRK2 signaling pathways to induce CCR9 internalization, thereby reducing leukemia cell infiltration and metastasis." (PMID 26879872, 2016). "Our findings provided strong evidence for developing CCR9 antagonists to overcome chemokine-induced MDR in leukemia cells." (PMID 23326330, 2013). "The expression mRNA levels for CCR9 in other leukemias, lymphomas or myelomas is much lower, although about 30% of the tumor samples in Splenic marginal zone lymphoma and about 20% of the samples in Hairy cell leukemia, Mantle cell lymphoma or Hodgkin lymphoma express high levels of CCR9 mRNA." (PMID 35967322, 2022). "CCR9 is closely related to the infiltration of leukemia cells." (PMID 33743810, 2021). "The chemotaxis and adhesion effects on leukemia cells were ablated when CCR9 was internalized on the T-ALL CD4+ T cells, which suggests that CCR9 is closely related to the infiltration and metastasis of leukemia cells." (PMID 26879872, 2016). "Further studies showed that CCL25/CCR9 induces MOLT4 cell polarization and microvilli absorption to participate in leukemia infiltration and trafficking via the RhoA-ROCK-MLC and ezrin pathway." (PMID 26879872, 2016). "The expression of the CCR9 chemokine receptor gene is limited in normal tissues, but the analysis presented here demonstrates that CCR9 is over-expressed in >80% of T-ALL leukemia patients, and in a considerable fraction of other hematopoietic and non-hematopoietic tumors." (PMID 35967322, 2022). "Interestingly, the Notch pathway has been shown to indirectly control the expression levels of CCR9 (and CCR5) in T-ALL cell lines and patient-derived primary leukemia cells, and subsequent biological effects such as cell proliferation and migration." (PMID 29666622, 2018). "Therefore, inhibiting CCL25/CCR9 may be a potential therapeutic strategy for treating leukemia patients, and it is of great significance to further explore the role of CCL25/CCR9 in leukemia." (PMID 33743810, 2021).
lung carcinoma (10 papers, 2015 to 2025). "The expression of the chemokine receptor CCR9 has been reported to be associated with improved prognosis in human lung cancer patients." (PMID 39335552, 2024). "In our study, the survival of advanced lung cancer treated with immunotherapy was significantly reduced in those patients with high baseline levels of CCR9+ or CCR10+ CD4+ T cells, or CXCR4+ CD8+ T cells." (PMID 35740564, 2022). "Similar to gut, the lung is one of the largest mucosal sites, and studies have shown an important role for CCR9 in promoting migration and suppressing apoptosis of lung cancer cells." (PMID 34939151, 2021). "The CCR9/CCL25 axis could promote the proliferation of lung cancer cells by inhibiting the apoptosis of tumor cells." (PMID 36003306, 2022). "Chemokines, particularly the CCR9/CCL25 and CXCL12/CXCR4 axes, play pivotal roles in lung cancer progression, immune cell recruitment, and tumor microenvironment remodeling." (PMID 40607416, 2025). "Gupta further revealed that lung adenocarcinoma cells produce TIMP-1 and TIMP-2, whereas lung SCC cells only express TIMP-2, suggesting that MMP and TIMP differential expression, mediated by the CCR9/CCL25 axis, influences lung cancer metastasis and invasion." (PMID 40607416, 2025). "Gupta reported that MMP-2 promotes CCR9/CCL25 interactions, facilitating lung cancer cell invasion and selective metastasis." (PMID 40607416, 2025). "This review systematically summarizes the biological functions and molecular mechanisms of the CCR9/CCL25 and CXCL12/CXCR4 axes in lung cancer." (PMID 40607416, 2025). "Interestingly, additional Transwell experiments showed that CCR9/CCL25 promoted the migration and invasiveness of lung cancer stem cells isolated from A549 cells, and the authors suggested that CCR9 or its ligand CCL25 could be used as a therapeutic target for lung adenocarcinoma." (PMID 35740564, 2022). "In lung cancer, the CCL25/CCR9 axis promotes cancer progression, but intratumoral delivery of CCL25 attracts CCR9+ CD8+ T cells to infiltrate the tumor and enhances CD47-targeted immunotherapy in a murine TNBC model." (PMID 34771505, 2021). "CCR9 expression is increased in various cancers (breast, prostate, ovarian and lung cancer), and CCL25/CCR9 signaling has been found in several tumors." (PMID 32957689, 2020). "Although no previous study has investigated the relationship between CCR9 and chemotherapy in lung cancer, interestingly, among the lung adenocarcinoma patients who received postoperative platinum-based chemotherapy, the patients with negative CCR9 expression had a significant better prognosis." (PMID 26168791, 2015). "Although the prognostic significance of CCR9 expression has not been previously examined in NSCLC, existing evidence suggested that CCR9-CCL25 axis is associated with cancer aggressiveness, and it might be used as a potential prognostic indicator in lung cancer." (PMID 26168791, 2015).